VCY1B (variable charge Y-linked 1B)
Description:
May mediate a process in spermatogenesis or may play a role in sex ratio distortion.
Synonyms: BPY1B
Tractability: No criterion of Open Targets' tractability assessment is met for any kind of drug.
Gene: Protein-coding gene on chromosome Y (14,056,227 to 14,056,958, forward strand). Ensembl gene ENSG00000129862.
Gene Ontology:
Molecular function: protein binding
Biological process: brain development
Homologues: Paralogues in human: VCY (100% identical), VCX3B (90% identical), VCX3A (89% identical), VCX (87% identical), VCX2 (85% identical).
Diseases named in the same sentence as VCY1B in open-access papers:
VCY1B is named in the same sentence as 1 disease in open-access papers, as found by Europe PMC text mining. Sharing a sentence is not in itself a finding about the gene and the disease.
VCY1B shares sentences with these, for which no sentence is quoted: Azoospermia (1 paper).